NFAT5 (nuclear factor of activated T cells 5)
Description:
Transcription factor involved, among others, in the transcriptional regulation of osmoprotective and inflammatory genes. Binds the DNA consensus sequence 5'- [ACT][AG]TGGAAA[CAT]A[TA][ATC][CA][ATG][GT][GAC][CG][CT]-3'. Mediates the transcriptional response to hypertonicity. Positively regulates the transcription of LCN2 and S100A4 genes; optimal transactivation of these genes requires the presence of DDX5/DDX17. Also involved in the DNA damage response by preventing formation of R-loops; R-loops are composed of a DNA:RNA hybrid and the associated non-template single-stranded DNA.
Synonyms: NF-AT5; TonEBP; KIAA0827; NFATL1; OREBP; NFATZ
Tractability: PROTAC: UniProt records ubiquitination sites on it; ubiquitination databases record sites on it.
Gene: Protein-coding gene on chromosome 16 (69,565,094 to 69,704,666, forward strand). Ensembl gene ENSG00000102908.
Subcellular location: Nucleus; Cytoplasm; Chromosome
Subcellular location (Human Protein Atlas): Nucleoplasm; Cytosol
Gene Ontology:
Molecular function: chromatin binding; DNA-binding transcription activator activity, RNA polymerase II-specific; protein binding; RNA polymerase II cis-regulatory region sequence-specific DNA binding; sequence-specific double-stranded DNA binding; DNA-binding transcription factor activity; DNA-binding transcription factor activity, RNA polymerase II-specific; DNA binding
Biological process: cellular response to cytokine stimulus; DNA damage response; positive regulation of canonical NF-kappaB signal transduction; positive regulation of leukocyte adhesion to vascular endothelial cell; positive regulation of mitochondrial translation; positive regulation of transcription by RNA polymerase II; R-loop processing; calcineurin-NFAT signaling cascade; cellular hyperosmotic response; signal transduction; transcription by RNA polymerase II; DNA-templated transcription; regulation of DNA-templated transcription; regulation of intracellular signal transduction; response to stress
Cellular component: chromosome; cytosol; nucleoplasm; nucleus; chromatin; cytoplasm; transcription regulator complex
Genetic constraint (gnomAD): Loss-of-function variants: 26 observed, 153.47 expected, observed/expected ratio (o/e) 0.17, 90% interval 0.12 to 0.23. The upper end of that interval is the gene's LOEUF score, 0.23, which puts it in group 1 of 6, group 1 being the genes least tolerant of losing a copy. Missense variants: 1,381 observed, 1,798.8 expected, observed/expected ratio (o/e) 0.77, 90% interval 0.73 to 0.8. Synonymous variants: 590 observed, 636.56 expected, observed/expected ratio (o/e) 0.93, 90% interval 0.87 to 0.99.
Gene-disease validity (ClinGen):
ClinGen rates the evidence that NFAT5 causes each of these diseases.
immunodeficiency disease (autosomal dominant): Limited. Disease in which there is a deficiency or defect in the mechanisms of immunity, either cellular or humoral.
Homologues: Orthologues: chimpanzee NFAT5 (99% identical), macaque NFAT5 (99% identical), dog NFAT5 (95% identical), rabbit NFAT5 (95% identical), mouse Nfat5 (93% identical), rat Nfat5 (91% identical), pig NFAT5 (91% identical), guinea pig NFAT5 (89% identical), tropical clawed frog nfat5 (61% identical), zebrafish nfat5b (41% identical), zebrafish nfat5a (41% identical), Drosophila melanogaster NFAT (20% identical). Paralogues in human: NFATC3 (16% identical), NFATC1 (15% identical), NFATC2 (15% identical), NFATC4 (12% identical).
Diseases named in the same sentence as NFAT5 in open-access papers:
NFAT5 is named in the same sentence as 188 diseases in open-access papers, as found by Europe PMC text mining. Sharing a sentence is not in itself a finding about the gene and the disease. The quoted sentences say what the papers report.
breast carcinoma (27 papers, 2013 to 2025). "NFAT5 expression was associated with poor prognosis in several cancers entities, including renal carcinoma and breast cancer." (PMID 26741489, 2016). "NFAT5 signaling cascade plays an important role in different diseases and modulating phenotypes associated with malignancy, but less is known about the resulting changes in gene expression that affect breast cancer." (PMID 25928084, 2015). "The osmosensitive transcription factor nuclear factor of activated T-cells (NFAT) 5, also known as tonicity enhancer binding protein (TonEBP), has been associated with the development of a variety of tumor entities, among them breast cancer, colon carcinoma, and melanoma." (PMID 25152734, 2014). "High salt exposure activates salt-inducible kinase-3 (SIK-3), a key regulator of mitogenic activity, while nuclear factor of activated T cells 5 (NFAT5) signaling upregulates VEGF expression in breast cancer cells, thereby facilitating cancer metastasis." (PMID 39944693, 2025). "Integrin α6β4 clustering, in the presence of chemoattractants, enhances NFAT5 transcriptional activity, promoting the migration of human breast carcinoma cells 66,257." (PMID 40421201, 2025). "In MCF-7 breast cancer cells, NFAT5 synergizes with STAT3, directing the inflammatory response toward IL17 and VEGFA production, supporting tumor inflammation and angiogenesis." (PMID 40421201, 2025). "High-salt mediated NFAT5/STAT3 signaling activation in breast cancer cell aids in proliferation and migration through activation of angiogenic factor VEGF-A." (PMID 39152497, 2024). "For instance, DDX17 regulates breast cancer pathology by promoting the transcription of NFAT5 target genes, and facilitates hepatocellular carcinoma metastasis by regulating alternative splicing, leading to the production of oncogenic RNA subtypes." (PMID 37239217, 2023). "NFAT5 is involved in the cellular response to osmotic pressure and in the migration of breast cancer cells." (PMID 35992805, 2022). "Enhance the transcription of NFAT5 target genes, but negatively regulate NFAT5 mRNA, then involve in precise regulation of breast cancer cell migration." (PMID 35992805, 2022). "NFATC1 binds to the ITGB3 promoter in osteoclast precursor cells, while NFATC2 and NFAT5 promote ITGA6/ITGB4-mediated cell invasion in breast cancer." (PMID 31730483, 2019). "In breast cancer, NFAT5 was demonstrated to be a putative biomarker of inflammatory breast cancer phenotype." (PMID 28983240, 2017). "Recent studies have shown that NFAT5 is involved in the pathogenesis of multiple cancers, including non-small cell lung cancer, leiomyoma, breast cancer, melanoma and renal carcinoma." (PMID 29052520, 2017). "Our study covered three SNPs (IGF1R rs2654981, NFAT5 rs7359387, NELF rs1059111) that were previously studied in the context of breast cancer risk." (PMID 25003827, 2014). "Sebastien Jauliac found that NFAT5 were expressed in invasive human ductal breast carcinomas and participate in promoting carcinoma invasion using cell lines derived from human breast and colon carcinomas." (PMID 25003827, 2014). "In colon and breast carcinoma cells NFAT5 drives the expression of the pro-metastatic factor S100A4, also known as metastasin." (PMID 25152734, 2014). "Additionally, beyond repressing AR and ERα activity, SAFB2 has been shown to suppress breast cancer progression by inhibiting the Wnt/β-catenin pathway via NFAT5." (PMID 40308776, 2025). "The CD4+T cells obtained from DLNs of tumor bearing CD4+NFAT5-KO mice following three stimulations with high salt did demonstrate a cytotoxicity of just 11 ± 4% (wild-type: 67 ± 9%; p < 0.05) on py230 breast cancer cells (E:T ratio 20:1)." (PMID 33918403, 2021). "Some previous studies showed activation of NFAT5 in colon, renal, and breast cancer." (PMID 32901097, 2021).
breast carcinoma (continued). "TF motif searching analysis suggested that TFs, such as NFAT5, might bind to the promoter and enhancer regions of hub lncRNAs and function in breast cancer biology." (PMID 32802855, 2020). "HOTAIR also silences miR-568 via recruitment of both EZH2 and LSD1 to the miR-568 promoter in breast cancer cells, leading to derepression of the miR-568 target NFAT5, which induces of EMT and invasion in breast cancer via transcriptional activation of calcium binding protein S100A4." (PMID 28430163, 2017). "Moreover, the expression of NFAT5 promotes breast cancer cells migration and tumor-driven angiogenesis." (PMID 28983240, 2017). "Various reports have also suggested involvement of NFAT5 in the pathogenesis of various tumor entities, such as non-small cell lung cancer, melanoma, leiomyoma, breast cancer, or colon carcinoma." (PMID 25152734, 2014). "The NFAT5 pathway has a significant effect on the pathogenesis of NSCLC, melanoma, breast cancer, and colorectal cancer." (PMID 36766810, 2023). "However, we found that NFAT5 has a completely different function in HCC than in other types of human cancers, including breast cancer, colon carcinoma, lung adenocarcinoma, renal cell carcinoma and melanoma." (PMID 29052520, 2017).
atherosclerosis (19 papers, 2012 to 2024). A disease characterized by the build-up of fatty material and calcium deposition in the arterial wall resulting in partial or complete occlusion of the arterial lumen. "AR and its transcription factor NFAT5 have been linked to several different disease states including cancer and atherosclerosis." (PMID 27536992, 2016). "Further cell-specific NFAT5 haploinsufficient in vivo experiments were, therefore, required to determine how NFAT5 deficiency in the cells of the lesion affected atherosclerosis progression." (PMID 22934063, 2012). "Additionally, several studies have previously reported that NFAT5 plays a key role in inflammatory processes of pathologies associated with cardiovascular diseases such as hypertension, atherosclerosis and diabetes mellitus." (PMID 36303007, 2022). "The stretch-induced translocation of NFAT5 therefore constitutes a novel regulatory mechanism underlying this phenomenon during stretch or wall stress-induced maladaptive remodeling processes which occur in the early phases of hypertension or atherosclerosis." (PMID 25520667, 2014). "However, once having anisotonic disorders, i.e., diabetes, the pathogenic response of NFAT5 could result in diabetes-related complications, such as diabetic nephropathy, diabetic retinopathy, and atherosclerosis." (PMID 33015193, 2020). "NFAT5-mediated pathological responses can result in human pathologies such as autoimmune diseases, acute kidney injury, hepatocellular carcinoma, atherosclerosis, and obesity." (PMID 38612478, 2024). "Besides, other transcription factors, such as growth arrest-specific homeobox (GAX) and Nuclear factor of activated T cells 5 (NFAT5), are also considered to alleviate the development of atherosclerotic lesions, loss of which is a major factor that contributes to atherosclerosis." (PMID 36604627, 2023). "NFAT5 can promote arterial smooth muscle cell proliferation and motility in vitro, thus preventing atherosclerosis." (PMID 35322734, 2022). "Additional in vivo data showed that Nfat5 is upregulated in the artery following acute vascular injury and in chronic atherosclerosis." (PMID 34064510, 2021). "Our findings suggest that miR-223 acts as a negative regulator of HASMC proliferation and motility by directly targeting NFAT5, thus providing potential therapeutic targets for atherosclerosis." (PMID 33373321, 2020). "Upregulation of NFAT5 is observed during diabetic complications such as atherosclerosis, diabetic nephropathy, and retinopathy." (PMID 33015193, 2020). "NFAT5 haploinsufficiency led to a significant reduction in aortic lesions in an in vivo model of atherosclerosis." (PMID 33015193, 2020). "The authors tracked the pro-atherosclerosis effect of NFAT5 to bone marrow-derived cells, suggesting that the cells responsible were of hematopoietic origin, although its specific type was not identified." (PMID 30949179, 2019). "We first observe that high-salt intake promotes atherosclerosis formation in the aortas of ApoE−/− mice, through inducing the expression of NFAT5, NLRP3, and IL-1β in endothelium." (PMID 31429763, 2019). "Macrophages play the most dominant role in enhancing lesion size, instability, and vascular inflammation, which led us to question if NFAT5 expression in macrophages was required for their normal function in atherosclerosis." (PMID 22934063, 2012). "The results of these studies demonstrate the importance of NFAT5 expression in the immune cells associated with chronic vascular disease and provide evidence for the role of NFAT5 in inflammation and atherosclerosis." (PMID 22934063, 2012). "In summary, we have identified that NFAT5 in BM-derived cells accelerates atherosclerosis, and we highlight the important role of NFAT5 in the regulation of macrophage migration." (PMID 22934063, 2012). "By utilizing NFAT5+/−ApoE−/− mice for HFD-induced atherosclerosis studies, we found that genome-wide NFAT5 haploinsufficiency inhibited atherosclerotic lesion development." (PMID 22934063, 2012).
atherosclerosis (continued). "Although the function of NFAT5 in atherosclerosis is undetermined, NFAT5 regulation in SMCs, ECs, and macrophages has been previously identified outside of the context of vascular disease." (PMID 22934063, 2012). "In vitro functional analysis of BM-derived macrophages demonstrated that NFAT5 is required for macrophage migration, which is a key event in the propagation of atherosclerosis." (PMID 22934063, 2012). "Our studies reveal that NFAT5 expression in BM-derived cells alone is responsible for enhancing atherosclerosis." (PMID 22934063, 2012). "Results from our BMT studies demonstrate that NFAT5 expression in BM-derived cells is required for atherosclerosis development in the mouse aorta." (PMID 22934063, 2012). "In addition, NFAT5 can also induce vascular endothelial cell apoptosis and inflammatory response, further contributing to the formation of atherosclerosis and CAS." (PMID 35322734, 2022). "In addition, NFAT5 had a role during diabetic complications such as atherosclerosis, diabetic nephropathy, and retinopathy." (PMID 35046888, 2021). "A more recent pathway of atherosclerosis pertains to the activation of NFAT5 by hypertonicity." (PMID 34064510, 2021). "Overall, these findings suggest that miR-223 inhibits the PDGF-BB-induced proliferation and motility of HASMCs by targeting NFAT5 and that miR-223 and NFAT5 may be potential therapeutic targets for atherosclerosis." (PMID 33373321, 2020). "Methods and Results: NFAT5+/−ApoE−/− mice were generated for in vivo atherosclerosis studies." (PMID 22934063, 2012). "Although undetermined, NFAT5 regulation of B- and T-cells in atherosclerosis could also account for the drastic reduction in lesion formation identified in NFAT5 haploinsufficient BM transplant mice." (PMID 22934063, 2012). "We sought to establish if NFAT5 levels in BM-derived cells alone could account for the reduction in atherosclerosis observed in NFAT5 haploinsufficient mice." (PMID 22934063, 2012). "We additionally show that BMDMs harvested from NFAT5+/− mice have impaired migratory abilities, and we believe these findings are noteworthy because macrophage migration into the lesion is a key event in the propagation of atherosclerosis." (PMID 22934063, 2012). "Due to the perinatal lethality of our NFAT5−/− mice, NFAT5+/−ApoE−/− mice were generated for atherosclerosis studies." (PMID 22934063, 2012). "Here we postulated that high-salt-induced NFAT5 controls the inflammasome activation by directly regulating NLRP3, which mediates the expression of inflammatory- and adhesion-related genes in vascular endothelium, resulting in the formation of atherosclerosis." (PMID 31429763, 2019). "Our study identifies NFAT5 as a new and essential transcription factor that is required for the early activation of NLRP3-inflammasome-mediated endothelium innate immunity, contributing to the formation of atherosclerosis under hypertonic stress induction." (PMID 31429763, 2019). "The transcription factor, NFAT5, has been shown to be up-regulated in relation to atherosclerosis and neointimal hyperplasia, consistent with a negative regulatory relationship with miR-206 (which was decreased in women with a history of PE in the present study)." (PMID 31899480, 2020). "Unlike our genome-wide NFAT5 haploinsufficient atherosclerosis studies, mice transplanted with NFAT5+/−ApoE−/− BM developed little to no lesions in the aortic arch and therefore could not be used for immunohistochemistry-based lesion composition analysis." (PMID 22934063, 2012).